CYP1B1 (cytochrome P450 family 1 subfamily B member 1)
Diseases named in the same sentence as CYP1B1 in open-access papers (continued):
Sharing a sentence is not in itself a finding about the gene and the disease.
tumor (continued). "In addition, the ability to inhibit CYP1B1 activity highlights a target for the development of an inhibitor, which would increase the efficacy of currently available cytotoxic agents at the site of the tumour." (PMID 15280921, 2004). "Interestingly the CYP1B1 protein is highly expressed in human tumours." (PMID 11875742, 2002). "Importantly this result gives insight into the functional role of CYP1B1 and provides evidence for the concept that CYP1B1 in tumours may be functioning as a growth suppressor enzyme." (PMID 11875742, 2002). "RNA‐seq demonstrated that, among the most altered genes involved in the tumor–stroma crosstalk, are ADAM12 and CYP1B1, which were proven to be key promoters of RCC tumorigenesis." (PMID 39806854, 2025). "In CRC models, the predominant expression of CYP2W1, CYP2S1, CYP1B1, and CYP2J2 suggests their potential functional involvement in tumour metabolism, xenobiotic processing and disease progression." (PMID 41174467, 2025). "The results showed that both the tumor tissue and the surrounding normal breast tissue expressed the enzymes CYP4B1 and others, such as CYP1B1, CYP2B6, CYP2C, CYP2D6, CYP2E1, and CYP11A1." (PMID 40723371, 2025). "Oxidative phosphorylation components (NDFs, COXs, TCIRG1, LHPP) and chemical carcinogenesis pathways involving reactive oxygen species (CYP1B1, GSTs, AKT2, IKBKB, MAPK3, MAP2K2) exacerbate DNA damage and promote tumour aggressiveness." (PMID 41007296, 2025). "The expression of CYP1B1, KMO, and TDO2 in tumor tissues was significantly upregulated in comparison with those in adjacent normal tissues." (PMID 38183155, 2024). "Phase I drug-metabolizing enzymes identified in the human prostate encompass CYP1A2, CYP1B1, CYP2C19, CYP2D6, CYP3A5, and CYP4B1, which are present in both normal and tumorous tissue." (PMID 38534761, 2024). "Next, we determined the correlation between CYP1B1 and ACSL4 in CRC tumor tissues, estimating by semiquantitative evaluation." (PMID 37059712, 2023). "aHSC release 12-HHTrE in a manner dependent on SCD and CYP1B1 and their conditioned medium reproduces the LTB4R2-mediated tumor-promoting effects of 12-HHTrE in HCC cells." (PMID 37156770, 2023). "However, it is of note that NAS and AhR-induced CYP1B1 accumulation in the mitochondria of tumor cells induces apoptosis, indicating that the suppression of NAS mitochondrial efflux may be another important modulator of mitochondrial melatonergic pathway effects in tumor cells." (PMID 37970210, 2023). "This tumor-suppressing role of CYP1A1 and CYP1B1 was supported by patient data which demonstrated an association between reduced target gene expression and worse overall survival." (PMID 37958428, 2023). "A population of CYP1B1-expressing aHSC in TME is relatively small but likely upregulates LTB4R2 in adjacent tumor cells via paracrine positive-forward regulation of the receptor that we disclosed." (PMID 37156770, 2023). "Furthermore, we also probed insight into the immune subtype, molecular subtype, tumor mutation burden (TMB), microsatellite instability (MSI), neoantigen, and immune-related pathways mediated by CYP1B1, which may provide a promising predictor and molecular target for clinical immune treatment." (PMID 36428734, 2022). "Cytochrome P450 1B1 (CYP1B1), a member of the cytochrome P450 (CYP) family, is highly expressed in tumor tissues, including in CRC, but its expression is lower than in normal tissues." (PMID 36505493, 2022). "Intratumoral Fn injection led to an increase of formate levels within tumour interstital fluids (TIFs), accompanied by an increased AHR, CYP1B1, SOX2 and ALDH1A1 (trendwise) gene expression." (PMID 35437333, 2022). "For example, the potent and selective CYP1B1 inhibitor, TMS, decreases cell growth and migration, as well as tumor growth in xenograft models in vivo." (PMID 36077068, 2022). "Chemical inhibitors of CYP1B1 are reported to increase the sensitivity of TNBC cell lines to CPT and other compounds in several tumor types." (PMID 36077068, 2022).
tumor (continued). "An overexpression of CYP1B1 and AhR has also been observed in inflammatory breast cancer (IBC) which correlated significantly with tumour grade, lymphovascular invasion, metastatic lymph nodes and the expression of Ki67 indicating cell proliferation." (PMID 33809117, 2021). "Based on previous studies in hepatocytes and a tumor cell line, proinflammatory cytokines IL-6 and TNF-α are involved in regulation of CYP1B1 expression." (PMID 32260461, 2020). "A cut-off point for relative expression of AHR and cytochrome 450 enzymes (CYP1A1, CYP1A2, and CYP1B1; markers of AHR activation) was determined to compare with the grade, stage, and tumor progression." (PMID 32907554, 2020). "The difference between CYP1B1-WT and CYP1B1-VAR tumours was significant for cisplatin and doxorubicin and below the limit of significance for irinotecan." (PMID 32565541, 2020). "In contrast, the tumours derived from our isogenic cell lines presented a significant resistance to the three drugs when they re-expressed CYP1B1, which may result from specific alterations of endogenous molecules by CYP1B1, such as oestrogens, the principal CYP1B1 substrate." (PMID 32565541, 2020). "Among these genes, six (HOXA6, STC2, HSD17B8, TFAP2A, CYP1B1, and HOXC8) were reported to be osteogenesis-/chondrogenesis-related genes, and five (ADRA1A, TSPYL5, TES, TNFRSF10D, and MBP) were reported to be tumor-suppressor genes." (PMID 31889115, 2019). "CYP1B1 and other CYP enzymes are regulated by the aryl hydrocarbon receptor (AHR), which is a ligand-activated transcription factor involved in the tumor-promoting properties of different environmental contaminants like PAHs." (PMID 31370872, 2019). "CYP1B1 is a key member of the CYP family, is highly expressed in tumor tissues and mediates the metabolism of a wide range of drugs." (PMID 26056584, 2014). "In the present study, we compared the pattern expression of CYP1A1, CYP1A2, CYP1B1, CYP2E1, CYP2W1, CYP3A4 and CYP3A5 in paired tumor and normal tissue of child patients with RMS." (PMID 24699256, 2014). "When comparing the relative mRNA concentration of CYP1B1, CYP2E1, CYP3A4, and CYP3A5 we detected in general higher regulation in tumor than their corresponding normal adjacent samples." (PMID 24699256, 2014). "Incubation of tumor microsomal protein with diosmetin and CYP1B1/CYP1A1 specific antibodies can improve the selectivity of the assay towards CYP1A1 and CYP1B1 isoforms." (PMID 24358191, 2013). "Thus, the levels of AhRR can be speculated to govern downregulation of CYP1B1 in tumor tissues." (PMID 22114726, 2011). "The cytochromes P450 CYP1B1 and CYP1A1 are differentially expressed within the tumour microenvironment compared with the surrounding normal tissue and have been proposed as targets for novel chemotherapeutic agents." (PMID 18454852, 2008). "In summary, we have demonstrated that the combination of EGCG+tamoxifen significantly reduced ER-negative tumour growth and that this was driven primarily by an enhanced effect by the decreased protein expression of the EGFR, mTOR, and CYP1B1." (PMID 18797454, 2008). "Furthermore, CYP1B1 hinders apoptosis by inhibiting the activation of caspase-1 (CASP1) and downregulating pro-apoptotic DAPK1, thereby providing tumor cells with a survival advantage." (PMID 41155673, 2025). "Consistent with our previous findings, we observed that CYP1B1 protein levels were significantly elevated in tissues exhibiting acquired resistance to sunitinib compared to primary tumour tissues without acquired resistance." (PMID 40435846, 2025). "CYP1B1, an inducible member of the CYP450 superfamily, serves as a crucial tumor biomarker." (PMID 38534761, 2024). "In all the tumors, CYP1B1 expression was independent of clinical parameters (gender, age, smoking, and tumor grade (T), except for an increase with lymphatic invasion (p < 0.02) and TNM (p < 0.05 respectively)." (PMID 39200369, 2024).
tumor (continued). "Our results also suggest that activated AhR may contribute to the tumor–stroma interaction (through CYP1A1 and CYP1B1) in diffuse GC." (PMID 39200369, 2024). "CYP1B1 is a member of the cytochrome P450 family, and CYP1B1 protein is highly expressed in most human tumor tissues but is low or not expressed in tumor-free tissues." (PMID 37686118, 2023). "The inhibition of CYP1B1 could detoxify carcinogenic PAHs, block the formation of PAH-DNA adducts, and suppress tumor formation." (PMID 35052622, 2022). "Analysis of all tumor samples showed a significant negative regression coefficient for CYP1B1 and CLDN7 expression values, consistent with our cell-based experiments." (PMID 36077068, 2022). "CYP1 analysis of TCGA-BRCA RNAseq data revealed CYP1A2 expression to be very low (max TPM = 1.3 with a median TPM = 0), while expression of CYP1A1 was high in a subset of tumours (max TPM = 78.3 but median TPM = 0.04) and CYP1B1 was generally more abundant (max TPM = 1611.7 and median TPM = 31.9)." (PMID 33809117, 2021). "Another, probably more ideal, strategy for CYP1B1-directed anticancer therapy is to rationally design prodrugs selectively activated by CYP1B1 in tumor tissues to cytotoxic metabolites without affecting normal cells." (PMID 34636736, 2021). "Several reports indicated high CYP1B1 expression in different tumours and a lack of expression in normal tissues, particularly hormone-responsive tumours such as breast, ovary, and prostate." (PMID 33692504, 2021). "No tumours were formed with CYP1B1-WT cells when less than 300 cells were injected, and there were only minor differences in tumour uptake between ALDH+ and ALDH− cells." (PMID 32565541, 2020). "An advantage of using a prodrug that is specifically designed to activate tumor-specific CYP1B1 is that it does not induce CYP1 enzymes." (PMID 31998435, 2020). "In relation to the stemness character of the CYP1B1-VAR cell line, we decided to explore the content in ALDH-positive (ALDH+) cells in both cell lines derived from the CAL27 cell line and their ability to generate tumours in immunocompromised mice." (PMID 32565541, 2020). "It is worth mentioning that high levels of CYP1B1 may increase the expression of AHR, therefore triggering a feed-forward loop that facilitates tumor progression." (PMID 31370872, 2019). "The GEP analysis showed that the down-regulated genes in tumor tissue were CYP3A4 in 56 patients (61%), CYP2C8 in 44 patients (48%), CYP2C19 in 30 patients (33%), CYP2D6 in 11 patients (12%), CYP3A5 in 7 patients (8%) and CYP1B1 in 2 patients (2%)." (PMID 29774122, 2018). "The genes found to be down-regulated in tumor tissue were CYP3A4 in 56 patients (61%), CYP2C8 in 44 patients (48%), CYP2C19 in 30 patients (33%), CYP2D6 in 11 patients (12%), CYP3A5 in 7 patients (8%) and CYP1B1 in 2 patients (2%)." (PMID 29774122, 2018). "However, several downstream AHR transcriptional targets, such as CYP1B1, ALDH and GST genes were found to be significantly reduced with more than two-fold differences observed between tumours and controls." (PMID 28649092, 2017). "Reduced biotransformation of MCA and tumor development in myeloid Hif-1αLysM−/− mice is thus explained by diminished ARNT expression and the subsequently reduced metabolic activation of PAHs by CYP1A1 and CYP1B1." (PMID 27015123, 2016). "The Cyp1b1(-/-) mice represented the elevated protection against DNA adduct formation induced by carcinogenic agents like DMBA or benzo[a,l]pyrene in tumors and also showed the blocking effect on tumor tissue metastasis induced by benzo[a]pyrene." (PMID 26981862, 2016). "To verify the inhibitory effects of decreasing CYP1B1 activity in combination with PTX treatment on tumor growth in vivo, we established a tumor xenograft mouse model of OC through the subcutaneous injection of 2×107 A2780TS cells into nude mice that had received sublethal irradiation." (PMID 25516145, 2015).
tumor (continued). "Several reports have shown that CYP1B1 can influence the regulation of tumor development; however, its role in RCC has not been well investigated." (PMID 26626260, 2015). "Most notable, however, were dramatic increases in the levels of 17β-HSD transcripts, which had decreased upon transfection of tumor cells, and very large increases of CYP1B1, which levels had not changed after transfection of tumor cells." (PMID 24848372, 2014). "Specifically CYP1B1 and CYP3A5 genes were significant upregulated in one tumor tissue (patients 4, and 7, respectively), while upregulation of CYP2E1 and CYP3A5 mRNAs were significant in 4 (patients 4, 5, 6 and 13), and 2 (patients 5 and 12) paired tumor samples, respectively." (PMID 24699256, 2014). "In contrast, CYP1B1 and CYP2E1 were most abundantly expressed and exhibited less inter-individual variability in both normal (mean Ct of 29.9 and 31.7, respectively) and tumor (mean Ct of 27 and 30.2, correspondingly) samples." (PMID 24699256, 2014). "Together with VWF, which is downregulated in tumor endothelial cells of CRC, CYP1B1 over-expression could promote angiogenesis in colon hepatic metastases." (PMID 24023955, 2013). "Our previous in vitro studies have shown that CYP1B1 is specifically localised to tumour cells, with no concomitant expression in normal tissue." (PMID 15280921, 2004). "Notably, the marked activation of CYP1A1, CYP1B1, and SLC16A6, coupled with the downregulation of tumour suppressors such as LINC01085 and CBS, underscores the potential of PM2.5 to promote oxidative stress, carcinogenesis, and therapy resistance in a mutation-dependent manner." (PMID 40559957, 2025). "Although not confirmed in the multivariate analysis, CYP1B1-positive patients had poorer survival in the univariate analysis, which may reflect tumor aggressiveness rather than prognostic value." (PMID 41155673, 2025). "Furthermore, pathways involved in xenobiotic metabolism (GSTs, DHDH, AKR7A2, HSD11B1L, CYP1B1, UGTs), drug metabolism, nucleotide metabolism, and homologous recombination (RAD51) reflect the tumour’s ability to adapt to environmental stressors and resist therapy." (PMID 41007296, 2025). "AhR may contribute to the tumor–stroma interaction (through CYP1A1 and CYP1B1) in diffuse GC." (PMID 39200369, 2024). "Interestingly, RSV has been reported to downregulate Cyp1b1, thereby increasing apoptosis induced by antimetabolites such as 5-FU and gemcitabine in gemcitabine-chemoresistant cholangiocarcinoma (Mz-ChA-1, HuCC-T1, CCLP1, and SG231) tumor models." (PMID 38026933, 2023). "This in silico analysis, together with our experimental data showing that CYP1B1 expression increase following cisplatin stimulation, support the hypothesis that the increase in CYP1B1 is due to cisplatin treatment and not the tumor itself." (PMID 37371125, 2023). "Thus, regulation of CYP1B1 by pathways in addition to the AHR may be important determinants to its expression and roles in tumor progression." (PMID 36077068, 2022). "Interestingly, the analysis indicates that CYP1B1 is likely regulated by two different mechanisms because basal CYP1B1 expression is retained even in AhR-low tumours, a feature that is not evident for CYP1A1." (PMID 33809117, 2021). "CYP1B1 and CYP1A1 may also affect the formation of advanced carcinoma and affect enzymes involved in the metabolism of chemotherapeutic agents that may help prevent tumor cytotoxicity." (PMID 31998435, 2020). "In addition to affecting gap junctions, rTNF was shown to work alone or in coordination with B[a]P (a HMW PAH) to upregulate CYP1B1 in a rat alveolar type II cell line (RLE-6TN), potentially increasing the metabolism of procarcinogens and therefore playing a role in early tumor development." (PMID 31018556, 2019).
tumor (continued). "Using as model systems ER-negative breast cancer cells, CAFs from a primary tumor, CAFs from a metastatic site and breast xenografts, we have determined that GPER may be an alternate route toward the regulation of CYP1B1 expression and function by estrogens in different biological targets." (PMID 29290975, 2017). "Similarly the expression of CYP1B1 mRNA in patients 12, 18 and 19 did not exhibit a significant difference between tumor and normal samples." (PMID 24358191, 2013). "Human CYP1B1 protein was detected in a variety of tumours but could not be detected in adjacent to normal tissues, where only mRNA was detected." (PMID 23873331, 2013). "However, RES inhibits CYP1A1 and CYP1B1, but still showed no decrease in tumor multiplicity when applied with DMBA in our study." (PMID 23835587, 2013). "Also the rate and magnitude of induction of CYP1B1 by cigarette smoke condensate was the highest in the non-malignant normal cells followed by the pre-malignant cells and then the tumor cells." (PMID 22114726, 2011). "CYP1A1 has been shown to be overexpressed in ovarian cancer cells and esophageal tumours, as opposed to normal cells and tissue, and CYP1B1 protein has been detected in a wide variety of tumours such as breast, brain, colon, and lung, whereas no protein was detected in corresponding normal samples." (PMID 18454852, 2008). "In contrast, to other cytochrome P450 enzymes, CYP1B1 is not expressed in human liver, but demonstrates enhanced expression of immunoreactive protein in a wide range of histologically diverse tumours including kidney, ovarian, breast and colon tumours." (PMID 15280921, 2004). "In addition selective overexpression of CYP1A1 and CYP1B1 may be utilized to target specific tumor types by the activation of non-toxic prodrugs that are selectively metabolized to cytotoxic products." (PMID 24358191, 2013). "This then led us to formulate a hypothesis for the functional role of CYP1B1 as a tumour suppressor enzyme or ‘rescue enzyme’ wherein CYP1B1 serves to activate certain non-toxic dietary components into growth inhibitory substances specifically within tumour cells containing the CYP1B1 enzyme." (PMID 11875742, 2002). "When the cultured tumor cells were treated with 1 μM B[a]P, there were no changes in mRNA expression of HIF-1α, its target genes, ARNT, AhR, and its target gene CYP1B1." (PMID 37305351, 2023). "Using real time quantitative RT-PCR, the gene expression pattern of CYP1A1, CYP1A2, CYP1B1, CYP2E1, CYP2W1, CYP3A4, and CYP3A5 were analyzed in tumor and adjacent non-tumor tissues from 13 child RMS patients." (PMID 24699256, 2014). "An inherent problem in determining CYP1B1 activity in tumour tissue is that there are no truly specific assays to distinguish between CYP1A1, CYP1A2 and CYP1B1 activity, which show close homology with one another and overlapping substrate specificity." (PMID 15280921, 2004). "In this investigation, we determined the expression of CYP1B1 and P450R in samples of normal kidney and RCC (11 paired normal and tumour and a further 15 tumour samples)." (PMID 15280921, 2004). "Thus, the aim of the present study was to determine the mRNA expression pattern of seven representative CYPs (e.g., CYP1A1, CYP1A2, CYP1B1, CYP2E1, CYP2W1, CYP3A4, and CYP3A5) in paired tumor and normal tissue of childhood patients with RMS." (PMID 24699256, 2014).